NKX2-3 (NK2 homeobox 3)
Description:
Transcription factor.
Synonyms: NKX2C; NKX2.3; CSX3; NKX4-3; NK2.3
Tractability: No criterion of Open Targets' tractability assessment is met for any kind of drug.
Gene: Protein-coding gene on chromosome 10 (99,532,942 to 99,536,524, forward strand). Ensembl gene ENSG00000119919.
Subcellular location: Nucleus
Subcellular location (Human Protein Atlas): Cytosol; Nucleoli
Gene Ontology:
Molecular function: sequence-specific double-stranded DNA binding; DNA-binding transcription factor activity, RNA polymerase II-specific; RNA polymerase II cis-regulatory region sequence-specific DNA binding; DNA binding
Biological process: cell differentiation; regulation of transcription by RNA polymerase II; regulation of DNA-templated transcription
Cellular component: chromatin; nucleus
Genetic constraint (gnomAD): Loss-of-function variants: 3 observed, 13.82 expected, observed/expected ratio (o/e) 0.22, 90% interval 0.098 to 0.56. The synonymous counts are far from expectation, so gnomAD's model fits this gene poorly and the ratio says little. Missense variants: 506 observed, 439.55 expected, observed/expected ratio (o/e) 1.15, 90% interval 1.07 to 1.24. Synonymous variants: 273 observed, 202.2 expected, observed/expected ratio (o/e) 1.35, 90% interval 1.22 to 1.49.
Homologues: Orthologues: chimpanzee NKX2-3 (99% identical), macaque NKX2-3 (98% identical), dog NKX2-3 (95% identical), pig NKX2-3 (93% identical), guinea pig NKX2-3 (91% identical), rat Nkx2-3 (90% identical), mouse Nkx2-3 (90% identical), zebrafish nkx2.3 (47% identical), tropical clawed frog nkx2-6 (36% identical), Drosophila melanogaster scro (27% identical), Caenorhabditis elegans ceh-24 (25% identical), Caenorhabditis elegans ceh-28 (20% identical), and 4 more. Paralogues in human: NKX2-5 (43% identical), NKX2-6 (40% identical), NKX2-1 (29% identical), NKX2-4 (29% identical), NKX2-2 (26% identical), NKX3-2 (23% identical), NKX2-8 (23% identical), NKX3-1 (20% identical), NKX1-1 (18% identical), NKX1-2 (17% identical), NKX6-1 (14% identical), NKX6-2 (13% identical), and 1 more.
Diseases named in the same sentence as NKX2-3 in open-access papers:
NKX2-3 is named in the same sentence as 58 diseases in open-access papers, as found by Europe PMC text mining. Sharing a sentence is not in itself a finding about the gene and the disease. The quoted sentences say what the papers report.
inflammatory bowel disease (9 papers, 2011 to 2023). A spectrum of small and large bowel inflammatory diseases of unknown etiology. "In humans, the potential pathogenic role of the Nkx2-3 transcription factor was found in inflammatory bowel diseases (Crohn’s and ulcerative colitis) so far and also suggested in spondylarthritis more recently." (PMID 32859051, 2020). "In genome-wide association studies (GWAS) single nucleotide polymorphisms of Nkx2-3 have been linked to inflammatory bowel diseases, often associated with ectopic intestinal lymphoid tissue formation." (PMID 30891037, 2019). "NKX2-3 plays a prominent role in immune and inflammatory responses and has been previously been implicated in inflammatory bowel disease pathogensis." (PMID 31171785, 2019). "However, NKX2-3 expression is regulated by transcription factor NFATC2 as identified by single nucleotide polymorphism (SNP)-analyses of patients suffering inflammatory bowel disease." (PMID 28151996, 2017). "Nkx2-3 as a transcriptional regulator of MAdCAM-1 controls vascular patterning in visceral lymphoid tissues in mice, and has been identified as a susceptibility factor for inflammatory bowel diseases in humans, associated with lymphoid neogenesis in the inflamed intestines." (PMID 30891037, 2019). "Findings revealed a diminished expression of NKX2-3 contributing to the pathogenesis and progression in inflammatory bowel diseases, largely attributed to the ED1 pathway." (PMID 38299096, 2023). "In a similar context, the regulation of the NKX2-3 on inflammatory bowel diseases was examined through cDNA microarrays in individuals exposed to PM2.5." (PMID 38299096, 2023). "However, the abnormal expression of NKX2-3 is mostly seen in digestive system diseases, which has been considered as a gene related to inflammatory bowel disease and Crohn's disease." (PMID 34423028, 2021).
Crohn disease (8 papers, 2009 to 2022). A gastrointestinal disorder characterized by chronic inflammation involving all layers of the intestinal wall, noncaseating granulomas affecting the intestinal wall and regional lymph nodes, and transmural fibrosis. "Amongst other genetic factors, Nkx2-3 has been identified as a susceptibility factor for both ulcerative colitis and Crohn's disease in humans, characterized by ectopic lymphoid neogenesis." (PMID 30891037, 2019). "Polymorphisms in NKX2-3 gene have been inconsistently associated with Crohn's disease (CD) and ulcerative colitis (UC)." (PMID 24473197, 2014).
diffuse large B-cell lymphoma (6 papers, 2016 to 2021). "On the other hand, NKX2-3 expression was found in only 2 out of 244 samples (0.8%) from diffuse large B-cell lymphoma (DLBCL), follicular lymphoma, mantle cell lymphoma, chronic lymphocytic leukaemia or multiple myeloma (P=0.001; Fisher exact test)." (PMID 27297662, 2016). "In addition, NKX2-3 expression has been detected in myelodysplastic syndrome, diffuse large B-cell lymphoma, T-ALL, and T-cell lymphoma, showing its oncogenic potential in both myeloid and lymphoid cell lineages." (PMID 34768865, 2021). "Here, we introduce the NKL-code in normal hematopoiesis and focus on deregulated NKL homeobox genes in B-cell lymphoma, including HLX, MSX1 and NKX2-2 in Hodgkin lymphoma; HLX, NKX2-1 and NKX6-3 in diffuse large B-cell lymphoma; and NKX2-3 in splenic marginal zone lymphoma." (PMID 31779217, 2019). "However, in marginal-zone B-cell lymphoma NKX2-3 expression is aberrantly activated via chromosomal juxtaposition to the B-cell receptor gene, and in diffuse large B-cell lymphoma activation of NKX2-1 is mediated by chromatin alterations but not via direct chromosomal rearrangement." (PMID 28151996, 2017). "Thus for example, NKX2-1 is ectopically expressed in diffuse large B-cell lymphoma (DLBCL), and the hematopoietic NKL homeobox genes NKX2-3 and NKX6-3 are overexpressed while MSX1 is downregulated in particular B-cell lymphomas." (PMID 30680064, 2018).
ulcerative colitis (5 papers, 2009 to 2020). An inflammatory bowel disease involving the mucosal surface of the large intestine and rectum. "In humans, overexpression of Nkx2-3 was found to be associated with both Crohn’s disease and ulcerative colitis through its effect on the regulation of PTPN2 expression, VEGF and MADCAM-1 signaling, and the production of endothelin-1." (PMID 32859051, 2020).
B-cell lymphoma (4 papers, 2016 to 2019). "Our study reveals NKX2-3 as a bona fide oncogenic driver in marginal-zone B-cell lymphomas, and provides an experimental mouse model to study the functional biology and therapy of this lymphoma entity." (PMID 27297662, 2016). "Here, the authors show that NKX2-3 is a bona fide oncogenic driver in marginal-zone B-cell lymphoma and that it promotes lymphomagenesis by shaping lymphocyte dynamics and promoting BCR signalling." (PMID 27297662, 2016). "Collectively, these data show that Eμ-NKX2-3 mice generated tumours mirroring the spectrum of human NKX2-3-expressing B-cell lymphomas." (PMID 27297662, 2016). "Therefore, NKX2-3 gene expression is deregulated by chromosomal translocations involving antigen receptor loci in B-cell lymphoma." (PMID 27297662, 2016). "Some of these identified genes have been previously shown to be deregulated in subsets of particular B-cell lymphomas, including HLX in HL, MSX1 in MCL, NKX2-1 in DLBCL, and NKX2-3 in SMZL, MALT lymphoma and DLBCL." (PMID 30308041, 2018). "Of note, NKL homeobox genes HLX, NKX2-1, NKX2-3, NKX6-3 and MSX1 are deregulated in B-cell lymphoma and show aberrant activity in T-ALL as well which might indicate similar oncogenic functions in both lineages of lymphoid malignancies." (PMID 29581848, 2018).
colorectal cancer (4 papers, 2021 to 2022). A primary or metastatic malignant neoplasm that affects the colon or rectum. "NKX2-3 and SLC25A28 were associated with CD, IBD, colorectal cancer, type I diabetes mellitus, and rheumatoid arthritis." (PMID 35464478, 2022). "According to available data, NKX2–3 has been demonstrated to be down-regulated in colorectal cancer, and it may contribute to the sporadic colorectal cancer by regulating the Wnt signaling pathway." (PMID 33402116, 2021). "A study has found that NKX2-3 could regulate the Wnt signaling pathway and then play a critical role in the pathogenesis of colorectal cancer and could be a new biomarker for clinical practice, including early diagnosis and subsequent therapy." (PMID 34423028, 2021). "NKX2–3 may also be classified as biomarker to predict the effects of primary advanced colorectal cancer patients who will undergo FOLFOX4." (PMID 33402116, 2021). "Moreover, NKX2-3 modulates the development of colorectal cancer by regulating the Wnt signaling pathway." (PMID 34457116, 2021).
splenic marginal zone lymphoma (4 papers, 2016 to 2021). Splenic marginal zone lymphoma is a rare, indolent B-cell non-Hodgkin lymphoma characterized by abnormal clonal proliferation of mature B-lymphocytes with involvement in the spleen, bone marrow and, frequently, the blood. "Further quantitative PCR studies revealed increased expression of NKX2-3 in a subset of patients with extranodal and splenic marginal-zone lymphomas (SMZLs), but not in other B-cell malignancies." (PMID 27297662, 2016).
head and neck squamous cell carcinoma (3 papers, 2021 to 2025). A squamous cell carcinoma that arises from any of the following anatomic sites: lip and oral cavity, nasal cavity, paranasal sinuses, pharynx, larynx, and salivary glands. "NKX2-3 has also been identified as a prognostic signature for head and neck squamous cell carcinoma in previously published studies." (PMID 34220946, 2021). "NK2 homeobox 3 (NKX2-3) has been reported as a prognostic factor in head and neck squamous cell carcinoma (HNSCC)." (PMID 37705968, 2023).
Hodgkins lymphoma (3 papers, 2018 to 2019). A heterogeneous group of malignant lymphoid neoplasms of B-cell origin characterized histologically by the presence of Hodgkin and Reed-Sternberg (HRS) cells in the vast majority of cases. "Prominent examples for B-cell malignancies that aberrantly overexpress NKL-code members HLX and NKX2-3 are Hodgkin lymphoma (HL) and splenic marginal zone lymphoma." (PMID 31141539, 2019).
mantle cell lymphoma (3 papers, 2016 to 2018). Mantle cell lymphoma is a rare form of malignant non-Hodgkin lymphoma affecting B lymphocytes in the lymph nodes in a region called the ``mantle zone''. "Deregulated NKL homeobox genes have been described in B-cell malignancies as well including MSX1 in mantle cell lymphoma, NKX2-1 in DLBCL, and NKX2-3 in marginal zone B-cell lymphoma." (PMID 29581848, 2018).
marginal zone B-cell lymphoma (3 papers, 2016 to 2018). "This study implicates oncogenic NKX2-3 in lymphomagenesis, and provides a valid experimental mouse model for studying the biology and therapy of human marginal-zone B-cell lymphomas." (PMID 27297662, 2016). "In marginal zone B-cell lymphoma NKX2-3 is aberrantly activated and acts as an oncogene." (PMID 28151996, 2017). "Overall, these data indicate that NKX2-3 is normally not expressed in mature B lymphocytes, but its aberrant expression is preferentially observed in a subset of patients with marginal-zone lymphomas (including SMZL and MALT lymphomas)." (PMID 27297662, 2016). "Here we show that NKX2-3 is overexpressed in tumour cells from a subset of patients with marginal-zone lymphomas, but not with other B-cell malignancies." (PMID 27297662, 2016).
prostate carcinoma (3 papers, 2021 to 2022). A carcinoma that arises from epithelial cells of the prostate gland. "An ARG, known as NKX2-3 demonstrates overexpression in prostate cancer patients, and is associated with poor overall survival, lymph node metastasis and reduced capacity of PDCD1 inhibitors." (PMID 35317831, 2022). "This integrated study of multiple databases opens up a new way for the use of NKX2–3 as fresh biomarkers or molecular targets in potential diagnostic and therapeutic strategies for prostate cancer." (PMID 33402116, 2021). "NKX2-3 can also be used as a diagnostic marker for prostate cancer." (PMID 34457116, 2021). "Further studies reveal an interaction between MIR205 and NKX2-3 that determines the therapy response of prostate cancer patients." (PMID 35317831, 2022). "Among them, five autophagy-related genes (ARGs) including ATG9B, DNAJB1, HSPB8, NKX2-3 and TP63 demonstrate remarkable association with prostate cancer development." (PMID 35317831, 2022). "In order to further understand the mechanism of NKX2–3 in prostate cancer, GSEA analysis was proformed." (PMID 33402116, 2021). "To further test the correlation of NKX2–3 with immunotherapy response of prostate cancer, we further analyzed the relationship between NKX2–3 and PD-1 (programmed cell death 1, PDCD1)." (PMID 33402116, 2021). "Then, the effect of NKX2–3 on the OS of prostate cancer was analyzed by cBioPortal database." (PMID 33402116, 2021). "Our data showed that as the expression of NKX2–3 increased, the expression of PD-1 decreased, thus NKX2–3 was negatively correlated with PD-1 in prostate cancer." (PMID 33402116, 2021). "We further leveraged the complementary value of DEMs and ARGs and showed that miR-205 could specifically bind the autophagy-related gene NKX2–3, and NKX2–3 may be a potential predictive marker for the efficacy of anti-PD-1 therapy in prostate cancer." (PMID 33402116, 2021). "In our study, the expression of autophagy-related gene NKX2–3 was significantly up-regulated in prostate cancer tissues compared to the non-tumor tissues." (PMID 33402116, 2021).
acute myeloid leukemia (2 papers, 2017 to 2020). Acute myeloid leukemia (AML) is a group of neoplasms arising from precursor cells committed to the myeloid cell-line differentiation. "Furthermore, NKX2-3 is expressed during myelopoiesis and behaves as a tumor suppressor gene in acute myeloid leukemia subtypes." (PMID 28151996, 2017).
colon cancer (2 papers, 2017 to 2020). "In colon cancer cell lines NKX2-3 regulates AUTS2 as well, suggesting a direct regulatory connection." (PMID 28151996, 2017).
leukemia (2 papers, 2017 to 2023). A malignant (clonal) hematologic disorder, involving hematopoietic stem cells and characterized by the presence of primitive or atypical myeloid or lymphoid cells in the bone marrow and the blood. "In the current study, we first utilized bioinformatics analysis to ascertain the dysregulated genes associated with autophagy in NPM1-mutated leukemia and obtained three genes including TUSC1, NKX2-3, and TP53INP2." (PMID 36675134, 2023).
melanoma (2 papers, 2021 to 2025). A malignant, usually aggressive tumor composed of atypical, neoplastic melanocytes. "NKX2‐3, another DMG related to HNSCC is one of the most critical epigenetic markers associated with the pathogenesis of human melanoma cell lines." (PMID 34313009, 2021).
T-cell lymphoma (2 papers, 2019 to 2021). "The most widespread overexpressed NKL homeobox genes in T-cell lymphomas were HHEX, HLX, MSX1 and NKX2-3, all members of the NKL-code." (PMID 31143370, 2019).
Arthritis (1 paper, 2020). Inflammation of a joint. "Since the Nkx2-3 mutation affects mostly the B lymphocyte development and recirculation, we hypothesized that the activation of B cells might be impaired, which, in turn, led to ameliorated arthritis." (PMID 32859051, 2020). "Since Nkx2-3 knock-out mice were present with severe splenic developmental defects, we were curious to test whether rhG1-induced arthritis could be observed in them." (PMID 32859051, 2020).
asplenia (1 paper, 2020). "It is, therefore, unclear at the moment which cellular process exerted by NKX2‐3 are at the basis of asplenia pathogenesis." (PMID 31498527, 2020). "It is currently unclear why asplenia is not a feature associated with NKX2‐3 mutations in humans." (PMID 31498527, 2020).
breast carcinoma (1 paper, 2021). "Expression of the six BCPRS genes (IFNA13, HEY1, NKX2-3, NR2F1, POU5F1, and YY1) in breast cancer tissues was analyzed using Tabula Muris's FACS and droplet methods." (PMID 34457116, 2021). "In summary, BCPRS and BCPRS-related genes (HEY1, IFNA13, NKX2-3, NR2F1, POU5F1, and YY1) can be used to evaluate the immune microenvironment and tumor purity in breast cancer patients." (PMID 34457116, 2021). "NKX2-3 and IFNA13 showed low expression levels in normal breast tissues, however, were highly expressed in breast cancer tissues." (PMID 34457116, 2021). "A multivariate Cox regression model was employed to establish a predictive model containing 6 characteristic genes (HEY1, IFNA13, NKX2-3, NR2F1, POU5F1, and YY1) correlated with the prognosis of breast cancer." (PMID 34457116, 2021). "The low expression level of POU5F1 and YY1 and high expression level of HEY1, IFNA13, NKX2-3, and NR2F1 were significantly related to poor prognosis in breast cancer." (PMID 34457116, 2021). "Furthermore, neural network-based deep learning models were established to predict breast cancer cell types using BCPRS-related genes (HEY1, IFNA13, NKX2-3, NR2F1, POU5F1, and YY1)." (PMID 34457116, 2021). "Therefore, a neural network-based model was constructed to predict cell types in breast cancer tissues based on genes YY1, POU5F1, NKX2-3, NR2F1, HEY1, and IFNA13." (PMID 34457116, 2021).
colitis (1 paper, 2020). Inflammation of the colon. "In mice, the absence of Nkx2-3 proved to be protective in DSS-induced colitis through an IL-22-independent mechanism." (PMID 32859051, 2020).
colorectal adenocarcinoma (1 paper, 2023). The most common type of colorectal carcinoma. "Similarly, SFRP2, NKX2-3, and ALB were also a part of the machine learning model for the prediction of liver metastasis in colorectal adenocarcinoma." (PMID 37887568, 2023).
erythroblastic leukemia (1 paper, 2021). "NKX2-4 is aberrantly expressed in erythroblastic leukemia cell line OCI-M2 and represses FLI1, while NKX2-3 is aberrantly expressed in megakaryoblastic leukemia cell line ELF-153 and activates FLI1." (PMID 34768865, 2021).
lymphoma (1 paper, 2016). A malignant (clonal) proliferation of B- lymphocytes or T- lymphocytes which involves the lymph nodes, bone marrow and/or extranodal sites. "Transgenic expression of human NKX2-3 in mouse B cells induced the development of lymphomas recapitulating the principal clinical and biological characteristics of human SMZL." (PMID 27297662, 2016). "Accordingly, this observation suggests that human SMZL and NKX2-3-induced mouse lymphomas may follow a similar sequential model of tumour development." (PMID 27297662, 2016). "Finally, we used the NKX2-3-induced mouse lymphomas to evaluate the potential therapeutic efficacy of drugs targeting the BCR and downstream signalling molecules." (PMID 27297662, 2016). "Finally, splenic lymphomas could be propagated in immunodeficient Rag2−/−IL2γc−/− mice, demonstrating the malignant potential of transformed NKX2-3-positive cells." (PMID 27297662, 2016). "In both lymphomas, increased NKX2-3 expression was observed with respect to non-tumoral B lymphocytes." (PMID 27297662, 2016). "Interestingly, these P3 lymphoma cells exhibited higher expression levels of LFA-1 and CXCR4 in comparison to NKX2-3-negative SMZL samples." (PMID 27297662, 2016).
lymphopenia (1 paper, 2016). Reduction in the number of lymphocytes. "Therefore, expression of NKX2-3 in lymphocytes led to lymphopenia in PB and to a progressive splenomegaly with marginal-zone B-cell expansion, leading to a profound disorganization of the normal splenic architecture." (PMID 27297662, 2016).